GSK3B (glycogen synthase kinase 3 beta)
Diseases named in the same sentence as GSK3B in open-access papers (continued):
Sharing a sentence is not in itself a finding about the gene and the disease.
diabetes (continued). "The Xiaotangzhike pill attenuates the progression of diabetes through the mediation of the Akt/GSK-3β axis." (PMID 36588590, 2022). "The literature review suggests that in diabetes, dysfunction of insulin and altered GSK-3β signaling in the brain contribute to the tau hyperphosphorylation, thereby potentially increasing the risk of developing AD." (PMID 34725612, 2021). "Ischemic preconditioning (IPC) is blocked by diabetes mellitus through activation of glycogen synthase kinase 3-beta (GSK3β), which is also a critical mediator for several pharmacological agents conferring cardioprotection." (PMID 34445586, 2021). "Glycogen synthase kinase 3β (GSK-3β) is an intermediate multifunctional serine/threonine kinase having diverse physiological pathways and involved in numerous diseases, like diabetes, inflammation, cancer, Alzheimer’s disease, and bipolar disorder." (PMID 33809065, 2021). "Western blot showed an increase in the protein levels of GSK3B, Nrf2, and P38 in rats with diabetes mellitus in comparison with the control group." (PMID 34249265, 2021). "In the nucleus and mitochondria, activation of apoptotic signalling promotes the active form of GSK3β.18, 19 During diabetes, the changed distribution of different forms of GSK3β is still unclear." (PMID 32163656, 2020). "Knockout of AKAP150 reverses impaired BK channel‐mediated vascular dysfunction through the Akt/GSK3β signalling pathway in diabetes mellitus." (PMID 32163656, 2020). "In summary, our study indicated that knockout of AKAP150 improves impaired BK channel‐mediated vascular dysfunction through the Akt/GSK3β signalling pathway in diabetes mellitus." (PMID 32163656, 2020). "In an alternative streptozotocin-induced diabetes model, elevated levels of GSK3β were accompanied with increased TNF, IL-1β, and IL-6 levels in the hippocampus." (PMID 32231133, 2020). "Some studies have shown that GSK-3β is upregulated in many disease states, including neurodegeneration, diabetes, inflammatory conditions, and some cancers." (PMID 32256957, 2020). "In view of this, GSK3β has attracted increasing attention as a potential therapeutic target in the treatment of diabetes." (PMID 33328854, 2020). "Our current studies have elucidated the important role of PK2 signaling cascade in DCM and Met ameliorates HG-induced cardiac damage through the PK2-mediated AKT/GSK3β pathway using in vivo diabetes animal models and in vitro HG-exposed cardiomyocytes." (PMID 32508669, 2020). "As one of the kinases of phosphorylating glycogen synthase (GS), GSK-3β is an essential factor leading to insulin resistance in the development of diabetes mellitus." (PMID 33299856, 2020). "Vildagliptin reversed diabetes-induced decrease of p-Akt, p-GSK-3β, brain-derived neurotrophic factor and nerve growth factor, thus against cognitive deficits and memory impairment." (PMID 31237881, 2019). "Diabetes-induced alterations in intracellular signaling pathways including the PI3K/Akt/GSK-3β pathway and enhanced inflammation and oxidative stress were suggested as possible underlying mechanisms for the lack of protection." (PMID 31198607, 2019). "Our data suggest that the AKT/GSK3β signalling pathway continues to be inhibited during testicular injury in diabetes and that Met effectively reverses the diabetes-induced inactivation of AKT." (PMID 31871550, 2019). "As the insulin signaling pathway controls the transport of glucose in hepatic cells, the dysregulation of IRS/AKT/GSK-3β insulin signaling pathway is a key determinant of the glycemic response showed in uncontrolled diabetes." (PMID 31442295, 2019). "To further elucidate the potential mechanism underlying diabetes-induced testicular damage, we determined the effects of the AKT/GSK3β signalling pathway on testicular damage." (PMID 31871550, 2019).
diabetes (continued). "Our results suggest that Nrf2-HO-1 has a critical role in the regulation of HG-induced EMT through the modulation of the PI3K/Akt/GSK-3β activity, highlighting Nrf2-HO-1 as a potential therapeutic target in diabetes-induced nephropathy." (PMID 31467925, 2019). "The deregulation of GSK-3β is related to the development of diabetes, neurodegenerative disease, and bipolar disorder." (PMID 30154726, 2018). "One Akt target that has received attention in the context of AD, in particular for the cross-talk between AD and diabetes, is GSK-3β." (PMID 29122977, 2018). "GSK-3β participated in regulating numerous signaling pathways related to the development of diabetes, neurodegenerative disease, and bipolar disorder." (PMID 30154726, 2018). "Currently, GSK-3β inhibitors have great promise as drugs for the pharmacotherapy of severe pathologies such as cancer, AD, mood disorders, diabetes, stroke, and many others." (PMID 29561817, 2018). "On the contrary, inhibition of GSK-3β prevents the onset of diabetes by improving glucose tolerance and β-cell function." (PMID 30202421, 2018). "The studies to restore myocardial sensitivity to local ischemic conditioning in diabetes have focused on GSK3-β and the mPTP." (PMID 28690837, 2017). "Recently, diabetes has been found to increase the expression and activity of glycogen synthase kinase-3β (GSK-3β)." (PMID 29209632, 2017). "The results obtained in this study demonstrated, for the first time, that silymarin ameliorates diabetes-induced angiogenesis in brain endothelial cells through a GSK-3β-mediated inhibition of VEGF release." (PMID 29209632, 2017). "HG-mediated apoptotic cell death is relevant to such diabetic complications as neuropathy, nephropathy and cardiovascular disease and, in addition, GSK-3β activity is increased in diabetes." (PMID 27851811, 2016). "Our analysis of autophagy and its related signalling in the mouse aorta lays the foundation for future investigations of GSK3β and autophagy in the aorta and more specifically, aortic endothelial cells, in mouse models of diabetes." (PMID 27534430, 2016). "A focus of these studies was glycogen synthase kinase 3β (GSK3β), an enzyme whose activity is increased in both humans and experimental animals with diabetes." (PMID 27534430, 2016). "Our data showed that gemigliptin ameliorated diabetes-induced cardiac apoptosis, which was mediated by GSK3β and NAD(P)H oxidase." (PMID 26959365, 2016). "Increased GSK3β activity has been observed in skeletal muscle of humans with diabetes and in epididymal adipose tissue and hearts of diabetic mice." (PMID 27534430, 2016). "In CM-treated diet-STZ-reduced diabetic rats, decreased AKT and GSK-3β phosphorylation is responsible for the transcriptional expression of multiple antioxidants to prevent diabetes-related oxidative damage." (PMID 27274781, 2016). "In recent years, the over-activation of GSK3β in the brain has been reported to be involved in the pathophysiology of AD and of type-2 diabetes mellitus." (PMID 26110057, 2015). "Previous studies have suggested that abnormal activation of GSK3β and decreased levels of p-GSK3β can depress glycogen synthesis and inhibit the insulin signaling pathway, which contributes to in the induction of insulin resistance in diabetes mellitus." (PMID 26296196, 2015). "Due to its wide range of functions, GSK-3β is believed to be involved in various disease processes, including neurodegenerative diseases, diabetes mellitus, and cancer." (PMID 26292722, 2015). "In diabetes mellitus, increased basal GSK3β activity contributes to accelerated EPC cellular senescence, effect reversed by small molecule antagonism of GSK3β which enhances cell-based therapy following vascular injury." (PMID 24689035, 2014). "Together, these data indicate that diabetes-induced oxidative stress triggers BRB breakdown by a mechanism involving uPAR expression through VEGF-induced activation of the GSK3β/β-catenin signaling pathway." (PMID 23951261, 2013).
diabetes (continued). "It has also been shown that Rapamycin markedly decreased GSK3 phosphorylation in muscle of normoglycemic and diabetic P. obesus, indicating increased GSK3β activity, while diabetes was reversed in obese diabetic mice treated with GSK3 inhibitors." (PMID 23437106, 2013). "We have recently reported for the first time that the activation of GSK-3β played the pivotal role in diabetes-induced energy disarrangement and consequently pathological remodeling in the myocardium." (PMID 21822424, 2012). "We have demonstrated that diabetes-induced myocardial oxidative damage and inflammation mainly due to the activation of GSK-3β." (PMID 21822424, 2012). "This study suggests that diabetes-induced attenuation of myocardial protection mediated by IPC involves in the activation of GSK-3β." (PMID 21822424, 2012). "Both IPC- and Ipost-mediated myocardial protection is predominantly mediated by stimulating PI3K/Akt and associated GSK-3β pathway while diabetes-mediated pathogenic effects are found to be mediated by inhibiting PI3K/Akt and associated GSK-3β pathway." (PMID 21822424, 2012). "When we inactivated GSK-3β activity with its inactivator in diabetic mice, diabetes-induced myocardial damage were almost completely prevented." (PMID 21822424, 2012). "GSK3β inhibitors are under intense clinical investigation as therapeutics for several diverse diseases such as diabetes, depression, and neurodegeneration." (PMID 23166798, 2012). "On the other hand, p-GSK-3β expression increased with duration of diabetes in parallel with decreased Akt-mediated phosphorylation of GSK-3 at Ser 9 and correlated with increased phosphorylation of NF-H reflecting its affinity to NF-H." (PMID 19834568, 2009). "GSK-3β, a downstream target of Akt, is active in its dephosphorylated form, and its heightened activity exacerbates inflammation, fibrosis, and cardiac remodeling in diabetes." (PMID 40737341, 2025). "Moreover, glycogen synthase kinase-3 beta (GSK-3β) has been considered to play an important role in the pathogenesis of type 2 Diabetes Mellitus and AD, where it acts as “tau-kinase I” that contribute to the phosphorylation of tau protein in AD." (PMID 40381124, 2025). "In the diabetes-induced rat model and the high-fat diet Sprague Dawley (SD) rat model, aerobic exercise also reduced the activity of GSK-3β." (PMID 40469843, 2025). "While its role in regulating diabetes-induced oxidative stress injury is well studied, the role of GSK3β in regulating inflammation in the context of DN remains unclear." (PMID 39880090, 2025). "Thus, REDD1-dependent GSK3β activation contributes to both diabetes-induced oxidative stress and inflammation in the kidney." (PMID 39880090, 2025). "Notably, a variety of drugs alleviate diabetes mellitus through the Akt/GSK-3β/Fyn/Nrf2 signaling pathway." (PMID 40864777, 2025). "Indeed, reduced inhibitory phosphorylation of GSK3β at S9 and activation of its kinase activity has been reported in multiple preclinical models of renal injury, including diabetes." (PMID 39880090, 2025). "Hence, the modulation of these interconnected pathways using pharmacological agents (such as metformin, Wnt activators, or GSK3β inhibitors) offers promising potential in the management of both diabetes and osteoporosis." (PMID 40564223, 2025). "In addition, TF3 dietary intervention significantly increased the phosphorylation level of GSK3β, which led to the dephosphorylation of GSK3β induced by diabetes." (PMID 39272556, 2024). "Though more work will be needed to reveal the PI3K/AKT/GSK3β-involved accurate mechanism of action regulated by N-p-CO, the present findings clearly demonstrate that N-p-CO is exploitable as a new candidate for the prevention and treatment of diabetes." (PMID 38725660, 2024). "However, with progression to frank diabetes, persistent hyperglycemia fosters a seemingly paradoxical rise in GSK3β-pSer9 in the brain." (PMID 38416718, 2024).
diabetes (continued). "Hence, we next investigated if the expression and activities of GSK3β and protein kinase D1 were altered in arteries during diabetes." (PMID 38581667, 2024). "Therefore, in this study, we confirmed the anti-apoptotic effect of red pine bark by investigating the Akt/GSK-3β pathway and tau protein expression levels in the hippocampus of Sprague-Dawley (SD) rats with diabetes induced by streptozotocin (STZ)." (PMID 38881175, 2024). "These enzymes are linked to diabetes-induced neurodegeneration by driving processes such as cholinergic deficiency (AChE), amyloid plaque formation (BACE-1), inflammation and oxidative stress (DPP-4), and tau pathology (GSK-3β)." (PMID 39766390, 2024). "Particularly, key proteins of insulin signaling were investigated, i.e., insulin receptor substrate (IRS-1), protein kinase B (PKB/AKT), and glycogen synthase kinase-3 (GSK-3β), which have gained considerable attention from scientists for the treatment of diabetes." (PMID 39795155, 2024). "Our results suggest that GSK3β inhibition prevents EndMTs and reduces calcification in diabetes." (PMID 36983045, 2023). "However, in the context of diabetes, multiple factors, including the activation of GSK3β, can trigger a self-sustaining deleterious feedback loop, further enhancing the expression of these metalloproteases." (PMID 37762417, 2023). "Several GSK3β inhibitors are currently being studied as potential drugs for diabetes treatment, and based on our results, IMT504 could be a promising candidate on that list." (PMID 37568265, 2023). "Some research in recent years has focused on GSK‐3β related to both AD and diabetes mellitus." (PMID 37483119, 2023). "Similarly, we found GSK-3β upregulation to cause delayed GE by reducing levels/activity of gastric PI3K/Akt/Nrf2, Phase II enzymes, and BH4-nNOSα in an obesity-induced diabetes mouse model." (PMID 36979006, 2023). "However, in diabetes, the ability of Akt to phosphorylate GSK-3 is reduced, causing GSK3β to remain active and leading to cardiac apoptosis." (PMID 37274326, 2023). "In addition, the knockout of AKAP 150 (murine AKAP150, a homolog of human AKAP79) was reported to ameliorate vascular dysfunction in diabetes by improving BK channels through the Akt/GSK3β signaling pathway." (PMID 37760030, 2023). "We found here that ε4‐carried T2DM patients showed elevated GSK‐3β activity in periphery blood, which was positively correlated with diabetes duration, plasma HbA1c, and FPG level, which provided novel information to link ApoE gene polymorphisms and GSK‐3β with cognitive functions in T2DM patients." (PMID 37700547, 2023). "Overall, the data support a role for GSK3β in diabetes-induced retinal inflammation." (PMID 37392853, 2023). "GSK‐3β is an enzyme implicated in the phosphorylation of various proteins, and overactivity of GSK‐3β causes a failure to convert glucose to glycogen, which results in hyperglycaemia and diabetes mellitus." (PMID 37483119, 2023). "Importantly, GSK3β is known to control activation of NF-κB, which has been described as a promising target in the management of vascular complications of diabetes, including DR61,79." (PMID 36229454, 2022). "Recently, a lot of evidence has shown that GSK‐3β may be the potential link between diabetes mellitus (DM) and AD." (PMID 35445545, 2022). "Notably, with the augmented GSK3β activity in the animal models with diabetes or obesity, the level of S255 phosphorylation is significantly elevated, further boosting the detrimental effects of increased MG53 expression under these pathological conditions." (PMID 36337049, 2022). "Together, all these data designate GSK3β as a negative regulator of β-cell mass and function and suggest that this enzyme could be a relevant target for the regenerative therapy of diabetes." (PMID 36499613, 2022).
diabetes (continued). "Thus, it is possible that Akt2 knockout in the RPE has a protective effect against diabetes through upregulated Akt1, further inhibiting a GSK3β/NF-κB-regulated inflammatory response." (PMID 36229454, 2022). "Moreover, GSK3β downregulation by pharmacological or genetic modulators resulted in the stimulation of β-cell regeneration in neonatal diabetes induced by streptozotocin." (PMID 36499613, 2022). "Finally, to further elucidate the mechanism by which SG attenuated the diabetes-induced cognitive impairment, we need to explore the interaction between GSK3β, Tau and neuronal apoptosis." (PMID 36407319, 2022). "However, in type 2 diabetes mellitus, because of insulin resistance, the GSK‐3β phosphorylation pathway is blocked, liver glycogen synthesis is inhibited, and liver glycogen content decreases, resulting in increased blood sugar concentration." (PMID 35665440, 2022). "Thereafter, our work was consistent with these recent reports, verifying that XTZK could inhibit the progression of diabetes through the mediation of the Akt/GSK-3β axis." (PMID 36588590, 2022). "Among the analogues, B29 and B30 with 2-aminopyrimidine substitutions could significantly increase hepatocyte glucose uptake in HepG2 cells, with good inhibitory activity against GSK-3β, showing potential for the treatment of diabetes." (PMID 33809065, 2021). "Among the complications of diabetes, fibrosis is primarily ameliorated by inhibition of GSK-3β activity, which may be related to its involvement in glycogen anabolism." (PMID 33052244, 2020). "Altogether, it is likely that the commonly used AD biomarkers (increased GSK-3β activity, tau protein hyperphosphorylation and Aβ accumulation) are associated with memory impairment in patients with diabetes, suggesting the potential application of these biomarkers in DM patients." (PMID 32872672, 2020). "In contrast, SB216763-treated diabetic WT mice and cardiac-specific metallothionein-overexpressing transgenic mice (which are protected from diabetes-associated cardiomyopathy) showed neither GSK3β activation nor significant symptoms of cardiac inflammation." (PMID 32231133, 2020). "Interestingly, our previous studies showed that HFD can induce dysregulation of Akt/GSK3β signaling, including abnormal inactivation of Akt and activation of GSK3β in diabetic retinae." (PMID 32575075, 2020). "GSK3β has also become an important drug target in anticancer therapy, Obesity-Induced White Adipose Tissue Inflammation, diabetes, and central nervous system diseases." (PMID 31156373, 2019). "GSK-3β overexpression inhibits β-cell proliferation in mice, and induces diabetes." (PMID 30202421, 2018). "The mutual interaction between GSK-3β and Pin1 become evident also in experimental models of hereditary hemochromatosis, whereas homozygous patients carrying the HFE hemocromatosis mutation have enhanced risk of diabetes (“bronze diabetes”) if untreated." (PMID 30096758, 2018). "In this investigation, we tested the hypothesis that silymarin ameliorates diabetes-induced abnormal angiogenesis in the brain in a GSK-3β-mediated inhibition of VEGF release." (PMID 29209632, 2017). "GSK-3β inhibition inhibited diabetes-induced migration and VEGF release." (PMID 29209632, 2017). "Furthermore, we demonstrated the essential role of GSK-3β in diabetes-induced dysfunctional angiogenesis." (PMID 29209632, 2017). "Additionally, we demonstrated the potential role of GSK-3β in diabetes-induced abnormal angiogenesis." (PMID 29209632, 2017). "Our results showed that GSK-3β inhibition antagonizes diabetes-induced migration of HBEC-5i." (PMID 29209632, 2017). "While this disease mechanism still awaits confirmation in patients with BD, the striking results suggest abnormal GSK-3β activity as a common link between BD and diabetes mellitus supported by a potentially similar drug effect of valproic acid on GSK-3β in the pancreas and in the brain." (PMID 27389787, 2016).